GALNT14 (polypeptide N-acetylgalactosaminyltransferase 14)
Description:
Catalyzes the initial reaction in O-linked oligosaccharide biosynthesis, the transfer of an N-acetyl-D-galactosamine residue to a serine or threonine residue on the protein receptor. Displays activity toward mucin-derived peptide substrates such as Muc2, Muc5AC, Muc7, and Muc13 (-58). May be involved in O-glycosylation in kidney.
Synonyms: GalNAc-T14; GalNac-T10; FLJ12691; GALNT15
Tractability: Antibody: UniProt predicts a signal peptide or a membrane-spanning region. PROTAC: a small molecule that binds it is known.
Target class: Enzyme; Transferase
Gene: Protein-coding gene on chromosome 2 (30,910,467 to 31,155,202, reverse strand). Ensembl gene ENSG00000158089.
Subcellular location: Golgi apparatus membrane
Subcellular location (Human Protein Atlas): Golgi apparatus; Nucleoplasm
Pathways (Reactome):
Metabolism of proteins: O-linked glycosylation of mucins
Gene Ontology:
Molecular function: polypeptide N-acetylgalactosaminyltransferase activity
Biological process: protein O-linked glycosylation; protein O-linked glycosylation via N-acetyl-galactosamine
Cellular component: Golgi apparatus; Golgi membrane
Genetic constraint (gnomAD): Loss-of-function variants: 54 observed, 71.21 expected, observed/expected ratio (o/e) 0.76, 90% interval 0.61 to 0.95. The upper end of that interval is the gene's LOEUF score, 0.95, which puts it in group 4 of 6, group 1 being the genes least tolerant of losing a copy. Missense variants: 695 observed, 735.38 expected, observed/expected ratio (o/e) 0.95, 90% interval 0.89 to 1.01. Synonymous variants: 278 observed, 288.85 expected, observed/expected ratio (o/e) 0.96, 90% interval 0.87 to 1.06.
Homologues: Orthologues: macaque GALNT14 (99% identical), guinea pig GALNT14 (92% identical), rat Galnt14 (92% identical), mouse Galnt14 (91% identical), pig GALNT14 (91% identical), chimpanzee GALNT14 (91% identical), dog GALNT14 (90% identical), rabbit GALNT14 (87% identical), tropical clawed frog galnt14 (70% identical), zebrafish galnt14 (63% identical), Caenorhabditis elegans gly-5 (38% identical), Drosophila melanogaster Pgant5 (37% identical), and 2 more. Paralogues in human: GALNT16 (54% identical), GALNT2 (49% identical), GALNT11 (39% identical), GALNT13 (39% identical), GALNT6 (39% identical), GALNT1 (38% identical), GALNT3 (38% identical), GALNT4 (38% identical), GALNT10 (38% identical), GALNT5 (38% identical), GALNT12 (36% identical), GALNTL6 (35% identical), and 7 more.
Diseases named in the same sentence as GALNT14 in open-access papers:
GALNT14 is named in the same sentence as 59 diseases in open-access papers, as found by Europe PMC text mining. Sharing a sentence is not in itself a finding about the gene and the disease. The quoted sentences say what the papers report.
breast carcinoma (20 papers, 2010 to 2025). "Previous studies have reported an association between GALNT14 and the prognosis of a variety of cancers, including gastric cancer, cholangiocarcinoma, ovarian cancer, and breast cancer." (PMID 38024474, 2023). "For example, GALNT14 was found to be overexpressed in most breast cancer tissues and associated with lung metastasis." (PMID 38024474, 2023). "GALNT14 is a transmembrane protein with large intracellular domain that has been associated with multiple cancer processes, including the promotion of breast cancer metastasis to the lung." (PMID 34068954, 2021). "The association between cancer characteristics and GALNT14 protein expression has been studied in breast cancer." (PMID 32098271, 2020). "High expression of GALNT14 in advanced breast cancer was associated with shorter lung metastasis-free survival (p = 0.0015)." (PMID 32098271, 2020). "Further analysis of 129 breast cancer patients showed that high expression of GALNT14 in breast cancer tissues was associated with higher HER2 (76.7% vs. 58.1%, p = 0.038), higher clinical stages (p < 0.0001), and shorter DFS (p = 0.029)." (PMID 32098271, 2020). "Collectively, our findings uncover an unprecedented role for GALNT14 in the pulmonary metastasis of breast cancer and elucidate the underlying molecular mechanisms." (PMID 27982029, 2016). "Having uncovered the mechanisms underlying GALNT14-mediated breast cancer metastasis to the lung, we next sought to identify the upstream regulators that are responsible for the elevated GALNT14 expression in lung-metastatic BCCs." (PMID 27982029, 2016). "Furthermore, increased GALNT14 expression is associated with resistance to therapeutics in breast carcinoma." (PMID 37671061, 2023). "GALNT14 is associated with higher P-gp levels in adriamycin-resistant human breast cancer tissues." (PMID 36077753, 2022). "The chemosensitivity of breast cancer was also found to be associated with GALNT14." (PMID 32098271, 2020). "In conclusion, our study not only uncovered a novel function of GALNT14 in the lung metastasis of breast cancer and delineated the underlying molecular mechanisms but also suggests that this enzyme can be a potential therapeutic target for breast cancer treatment." (PMID 27982029, 2016). "For instance, GALNT14 is essential for P‐gp stability on the plasma membrane in breast cancer and is correlated with oxaliplatin resistance in colorectal cancer." (PMID 39844613, 2025). "In breast cancer, GALNT14 modulates tumor multidrug resistance and promotes cancer invasion by altering cell proliferation, motility, and EMT gene expression levels, while gene polymorphisms of GALNT16 are strongly associated with cancer susceptibility." (PMID 38244579, 2024). "Beyond, GALNT14 plays a role in migration, invasion, and proliferation of cells particularly in the development of breast carcinoma and supports epithelial-mesenchymal transition and metastasis." (PMID 37671061, 2023). "In breast cancer cell lines, GALNT14 O-glycosylation of FGFR1 primes breast cancer cells to respond to FGFR activation." (PMID 34068954, 2021). "GALNT14 promotes breast cancer metastasis to the lungs by enhancing the initiation of metastatic colonies and their subsequent growth into overt metastases." (PMID 32098271, 2020). "GALNT14 contributes to breast cancer invasion by altering cell proliferation and motility, by altering the expression levels of EMT genes, and by stimulating MMP-2 activity." (PMID 32733355, 2020). "Collectively, our results suggest that GALNT14 selectively potentiates breast cancer metastasis to the lung." (PMID 27982029, 2016). "Here, we report that GALNT14 promotes breast cancer metastasis to the lung by enhancing the initiation of metastatic colonies as well as their subsequent growth into overt metastases." (PMID 27982029, 2016).
breast carcinoma (continued). "Our study reveals that GALNT14 specifically promotes breast cancer metastasis to the lung, by accelerating the initiation of metastatic colonies as well as their subsequent growth into macrometastases." (PMID 27982029, 2016). "In the present study, we revealed that GALNT14 specifically promotes breast cancer metastasis to the lung by accelerating both of these events in the lung parenchyma." (PMID 27982029, 2016). "Here the authors show that GALNT14 promotes breast cancer metastasis to the lung by enhancing the initiation of metastatic colonies and subsequent growth." (PMID 27982029, 2016). "Taken together, our data indicate that GALNT14 expression correlates with lung metastasis in patients with advanced breast cancer." (PMID 27982029, 2016). "Our results suggest that GALNT14 augments the self-renewal properties of breast cancer cells (BCCs)." (PMID 27982029, 2016). "Collectively, our data suggest that GALNT14 not only promotes lung metastasis but also mammary tumour initiation." (PMID 27982029, 2016). "Because GALNT14 would contribute directly to malignant progression of breast carcinoma by altering the rate of cellular proliferation and promoting cell invasion and migration, this gene was suggested to be a novel therapeutic target for breast cancer." (PMID 26309160, 2015). "GALNT14 over-expression was reported to play a critical role in cell migration, invasion and proliferation of breast cancer by promoting the epithelial-mesenchymal transition of breast cancer cells." (PMID 26309160, 2015). "It has also been found that GALNT14 proteins are more abundant in breast carcinoma compared with normal tissues, but that the expression levels decrease in more advanced stages of cancer." (PMID 25295111, 2014). "GALNT14 regulates the stability of P‐gp, an efflux pump in the cell membrane which leads to an increase in the efflux of anticancer drugs outside the cell and the development of multidrug resistance in breast cancer." (PMID 37937323, 2023). "GALNT14 mRNA and protein are upregulated in the chemoresistant breast cancer cell line MCF7." (PMID 36077753, 2022). "GALNT14 is related to the chemosensitivity of breast cancer." (PMID 32680999, 2020). "GALNT14 expression also regulates multi-drug resistance in breast cancer cells." (PMID 32098271, 2020). "In a study conducted with the MCF-7 breast cancer cell line, overexpression of GALNT14 significantly enhanced cell proliferation, migration, and tumor invasion, while the knockdown of GALNT14 reduced clonogenicity and attenuated cell migration and cell invasion." (PMID 32098271, 2020). "Interestingly, GALNT14 knockdown attenuated the initial growth of mammary tumours only when 5 × 104 cells were injected, which led to decreased tumour volume at the later stage." (PMID 27982029, 2016). "Thus, the enhanced self-renewal of BCCs conferred by GALNT14 led us to examine the role of this enzyme during the initial stage of mammary tumour formation." (PMID 27982029, 2016). "Moreover, GALNT14 mediated O-glycosylation of EGF-containing fibulin-like extracellular matrix protein 2 (EFEMP2) which significantly increased the invasion ability of breast cancer cell lines (MCF-7 and MBA-MD-231)." (PMID 32098271, 2020). "Thus, we examined whether GALNT14 contributes to breast cancer metastasis to other organs, including the bones and brain." (PMID 27982029, 2016). "GALNT14 was found to be over-expressed in most breast cancer tissues (47/56, 83.9%), but in only 7/48 (14.6%) of non-malignant breast tissues." (PMID 32098271, 2020). "However, the GALNT14-mediated regulation of FGF signalling and its functional role in the lung metastasis of breast cancer remains unknown." (PMID 27982029, 2016).
hepatocellular carcinoma (15 papers, 2014 to 2025). A malignant tumor that arises from hepatocytes. "Applying a genome-wide association method followed by prospective validation, the single-nucleotide polymorphism (SNP) rs9679162 of GALNT14 was first discovered correlating with the therapeutic outcome in patients with hepatocellular carcinoma." (PMID 31888240, 2019). "Our recent studies also indicated a tight association between GALNT14 genotype and chemotherapy or chemoembolization responses in advanced hepatocellular carcinoma patients." (PMID 28418863, 2017). "The single nucleotide polymorphism (SNP) rs9679162 located on GALNT14 gene predicts therapeutic outcomes in patients with intermediate and advanced hepatocellular carcinoma (HCC), but the molecular mechanism remains unclear." (PMID 36376274, 2022). "Moreover, the single nucleotide polymorphisms (SNPs) of GALNT14-rs9679162 have been shown to predict therapeutic outcomes in patients with hepatocellular carcinoma as well as several other different types of gastrointestinal cancer." (PMID 32098271, 2020). "Also, SNPs on GALNT14 have been shown to be associated to the chemotherapy responses of patients with advanced hepatocellular carcinoma." (PMID 26309160, 2015). "Tenofovir is a major negative regulator of GALNT14 substrates and an unfavorable anti-hepatitis B drug in patients with hepatocellular carcinoma receiving sorafenib." (PMID 36077753, 2022). "As a carcinoma driver gene, GALNT14 was proved to participate in the tumorigenesis and progression in ovarian cancer, hepatocellular carcinoma, lung cancers, and so on." (PMID 36405691, 2022). "GALNT2, sharing a high amino acid sequence homology with GALNT14, regulates the malignant character of hepatocellular carcinoma by modulating the structure of short O-glycans on EGFR." (PMID 28388560, 2017). "N-acetylgalactosaminyltransferase 14 (GALNT14)-rs9679162 genotype is a prognostic predictor for chemotherapy response in advanced hepatocellular carcinoma." (PMID 27124048, 2016). "A GALNT14 single nucleotide polymorphism, rs9679162, has recently been found to be capable of predicting chemotherapy responses in patients with far-advanced hepatocellular carcinoma (HCC)." (PMID 25295111, 2014). "The protein product of the GALNT14 gene may serve oncogenic roles and regulate anti-cancer drug sensitivity in multiple cancers, including hepatocellular carcinoma, possibly through modulating downstream effector glycosylation." (PMID 38928347, 2024). "In patients with advanced hepatocellular carcinoma, linkage of the germline SNP marker rs9679162 with GALNT14 could be correlated with the objective response to the first course of 5-fluorouracil, mitoxantrone and cisplatin (FMP) chemotherapy." (PMID 27322213, 2016). "The role of GALNT14-rs9679162 in predicting therapeutic outcomes was initially established in advanced hepatocellular carcinoma (HCC) patients receiving chemotherapies." (PMID 31888240, 2019). "In hepatocellular carcinoma (HCC), the glycosyltransferase GALNT14 mediates O-glycosylation of PHB2, enhancing tumor cell proliferation, migration, and chemotherapy resistance through activation of the insulin-like growth factor 1 receptor (IGF1R) signaling cascade." (PMID 40868286, 2025).
ovarian carcinoma (15 papers, 2010 to 2025). A malignant neoplasm originating from the surface ovarian epithelium. "The clinical relevance of GALNT14 in chemotherapy resistance has been demonstrated in cisplatin-resistant ovarian cancer models, in which combination therapy targeting both GALNT14 and mTOR signaling promoted cell death." (PMID 41008983, 2025). "GALNT14 has emerged as a key regulator of both ferroptosis and apoptosis in ovarian cancer through its effects on epidermal growth factor receptor (EGFR) glycosylation and downstream mTOR pathway activation." (PMID 41008983, 2025). "Chemoresistant ovarian cancer cells exhibited increased GALNT14 expression, which led to enhanced tumor cell viability via the EGFR/mTOR signaling pathway." (PMID 37671061, 2023). "This suggests that GALNT14 provides a strategy to overcome cisplatin resistance in ovarian cancer patients." (PMID 36090052, 2022). "Accumulating evidence has shown that GALNT14 was over-expressed in tumors such as breast, lung, and ovarian cancer to promote the process of tumor malignancy." (PMID 36569869, 2022). "In another study on ovarian cancer, suppression of cell migration and altered cellular morphology were found to result from the knockdown of GALNT14 by small interfering RNA." (PMID 27322213, 2016). "Traditional chemotherapy and radiation therapy may also benefit from a combination of glycosylation-targeting approaches, as demonstrated by the inhibition of GALNT6 and GALNT14 expression in ovarian cancer." (PMID 41008983, 2025). "GALNT14, a member of the acetylgalactosaminyltransferases family, which can regulate the stability of EGFR proteins to inhibit the EGFR/mTOR pathway, has significantly higher levels of GALNT14 in cisplatin resistance ovarian cancer tissue compared to cisplatin sensitive ovarian cancer tissue." (PMID 39192972, 2024). "However, a recent study shows that GALNT14 is involved in the regulation of apoptosis and ferroptosis in ovarian cancer and contributes to the development of chemoresistance." (PMID 37671061, 2023). "Downregulation of GALNT14 significantly inhibits apoptosis and ferroptosis in ovarian cancer cells." (PMID 36077753, 2022). "GALNT14 expression is upregulated and correlated with ovarian cancer." (PMID 36077753, 2022). "The down regulation of GALNT14, which is up-regulated in ovarian cancer, inhibits the activity of mTOR pathway through O-glycosylation of EGFR, thereby inhibiting ferroptosis in ovarian cancer cells." (PMID 35784729, 2022). "GALNT14-rs9679162 genotype is a predictor of PFS, OS, and response to FMP chemotherapy FMP in HCC, and GALNT14 expression also affects chemoresistance in breast and ovarian cancer cells." (PMID 36077753, 2022). "Conversely, if the “TT” genotype correlates with a higher level of GALNT14, while the “GG” correlates with a lower level, then the GALNT14 protein in PDA has an oncogene-like function, similar to what has been reported in breast and ovarian cancer." (PMID 31888240, 2019).
neuroblastoma (9 papers, 2015 to 2024). Neuroblastoma (NB) is the most common solid, extracranial childhood tumor. "A GALNT14 mutation (c.802C > T) was identified as a neuroblastoma predisposition gene and was predicted to be functionally damaging by the PolyPhen2 (Polymorphism Phenotyping v2) and SIFT (Sorting Intolerant From Tolerant) scoring methods." (PMID 32098271, 2020). "Moreover, mutations identified in the GALNT14 gene have demonstrated it to be a potential neuroblastoma predisposition gene." (PMID 38928347, 2024). "Furthermore, high expression of GALNT14 was associated with a worse OS in a public dataset of 88 neuroblastoma samples." (PMID 32098271, 2020). "Furthermore, GALNT14 mutations have been associated with neuroblastoma predisposition." (PMID 36077753, 2022). "GALNT14 is located close to ALK on 2p23.1, a region previously discovered to be linked with neuroblastoma." (PMID 32098271, 2020). "Clinically, the GALNT14 level serves as a prognostic marker for neuroblastoma and non-small cell lung cancer (NSCLC)." (PMID 32098271, 2020). "Several germline and sporadic mutations predisposing to neuroblastoma development have been identified, including PHOX2B, anaplastic lymphoma kinase (ALK), polypeptide N-acetylgalactosaminyltransferase 14 (GALNT14), and MYCN." (PMID 28358317, 2017). "Interestingly, GALNT14 higher expression significantly correlates with a worse OS in a public dataset of 88 NB samples (Tumor Neuroblastoma public - Versteeg - 88 - MAS5.0 - u133p2), either considering all NB patients or cases with no MYCN amplification, which alone has a strong impact on the OS." (PMID 26309160, 2015).
melanoma (7 papers, 2010 to 2023). A malignant, usually aggressive tumor composed of atypical, neoplastic melanocytes. "High expression of peptidyl O-glycosyltransferase GALNT14 is found in melanoma cell lines contributing to the sensitivity to TRAIL by modifying DR4 or 5 through O-glycosylation to enhance the DISC formation through clustering of these receptors." (PMID 34299249, 2021). "Melanoma cells can use the downregulation of GALNT14 to attenuate TRAIL signaling at the receptor level." (PMID 34299249, 2021). "GALNT14 modulates death-receptor O-glycosylation in pancreatic carcinoma, non-small-cell lung carcinoma, and melanoma cells." (PMID 28388560, 2017). "In other tumors such as pancreatic carcinoma, non-small cell lung cancer and melanoma GALNT14 expression was observed to correlate with Apo2L/TRAIL sensitivity to proapoptotic signaling through O-glycosylation of Apo2L/TRAIL death receptors." (PMID 26309160, 2015). "Also, GALNT14 expression correlates with pro-apoptotic drug's sensitivity in pancreatic carcinoma, non-small-cell lung carcinoma and melanoma cell lines." (PMID 24504219, 2014). "GALNT14 promotes the O-glycosylation of death receptors 4/5 (DR4/5) and mediates tumor necrosis factor-related apoptosis-inducing ligand (TRAIL)-induced apoptosis in pancreatic carcinoma, non–small cell lung carcinoma, and melanoma cells." (PMID 36077753, 2022).